MOG (myelin oligodendrocyte glycoprotein)
Diseases named in the same sentence as MOG in open-access papers (continued):
Sharing a sentence is not in itself a finding about the gene and the disease.
optic neuritis (301 papers, 2010 to 2026). Optic neuritis is inflammation of the optic nerve, the nerve that carries the visual signal from the eye to the brain.The conditionmay cause sudden, reduced vision in the affected eye(s). "We present the case of a 31-year-old male with a prior history of MOG-associated optic neuritis (ON) who developed acute-onset dizziness and gait instability evolving over five days." (PMID 41635854, 2026). "This association is particularly strengthened when combined with unilateral optic neuritis at onset, where non-P42 MOG-IgG was associated with more than double the risk of relapse in adult patients." (PMID 41153632, 2025). "While MS and NMOSD were ruled out, tests for MOG-IgG were not available at the time of this study; therefore, some atypical cases of MOG-associated optic neuritis cannot be completely excluded." (PMID 41356327, 2025). "Myelin Oligodendrocyte Glycoprotein Antibody-Associated Disease (MOGAD) is a rare acquired demyelinating syndrome manifesting as optic neuritis (ON), transverse myelitis (TM), acute disseminated encephalomyelitis (ADEM), and brainstem encephalitis." (PMID 40463369, 2025). "Although bilateral involvement is more common in MOG-antibody-associated optic neuritis, unilateral cases have been reported, including those linked to SARS-CoV-2 infection and vaccination." (PMID 40026947, 2025). "Early diagnosis and prompt initiation of systemic corticosteroid therapy are essential to optimize outcomes, as MOG-associated optic neuritis often responds favorably to timely treatment." (PMID 40026947, 2025). "The emergence of MOG-immunoglobulin G (MOG-IgG) has defined a distinct entity, MOG-IgG-associated optic neuritis (MOG-ON), providing new perspectives for the diagnosis and treatment of optic neuritis (ON)." (PMID 41235231, 2025). "In the past few years, MOG-ON has enabled the identification of a subgroup with a clinical course distinct from other optic neuritis phenotypes, highlighting the diagnostic and prognostic value of MOG-IgG testing." (PMID 41235231, 2025). "This case highlights the importance of recognizing MOG antibody-associated optic neuritis as a rare but significant neuro-ophthalmological complication following SARS-CoV-2 vaccination." (PMID 40026947, 2025). "The clinical presentation of MOG-IgG seropositivity, papillitis, and extensive optic nerve involvement strongly supports the diagnosis of MOG antibody-associated optic neuritis." (PMID 40026947, 2025). "Optic neuritis has been observed in patients receiving rituximab for neurologic autoimmune disorders such as myelin oligodendrocyte glycoprotein antibody-associated disease (MOG AD), but is exceedingly rare in cancer patients." (PMID 41568391, 2025). "A diagnosis of MOG-associated unilateral optic neuritis following SARS-CoV-2 vaccination was established." (PMID 40026947, 2025). "Beyond optic neuritis, MOG-IgG has been implicated in recurrent, steroid-responsive uveitis, scleritis, and episcleritis, and sometimes in isolation." (PMID 41153632, 2025). "Myelin oligodendrocyte glycoprotein antibody-associated disease (MOGAD) is an autoimmune inflammatory demyelinating disorder that can manifest as optic neuritis, transverse myelitis, and acute disseminated encephalomyelitis." (PMID 40717732, 2025). "Conversely, optic neuritis associated with NMOSD or MOG-IgG often presents with severe vision loss worse than 20/400." (PMID 39975816, 2025). "Myelin oligodendrocyte glycoprotein (MOG) antibody-associated disease (MOGAD) is a demyelinating disease of the central nervous system (CNS) that manifests as optic neuritis, transverse myelitis, acute disseminated encephalomyelitis, and cortical encephalitis." (PMID 40904974, 2025). "Myelin oligodendrocyte glycoprotein-associated disease (MOGAD) has a wide phenotypic expression that includes optic neuritis, transverse myelitis, acute demyelinating encephalomyelitis (ADEM), as well as other neurologic syndromes." (PMID 38350984, 2024).
optic neuritis (continued). "Anti Myelin oligodendrocyte glycoprotein antibody-associated disease (MOGAD) is a childhood encephalitis presenting with recurrent optic neuritis, myelitis or encephalomyelitis, brainstem syndrome, or cerebral cortical encephalitis syndrome." (PMID 39651491, 2024). "Myelin-oligodendrocyte glycoprotein antibody-positive optic neuritis (MOGON) causes inflammatory demyelination of the optic nerve, leading to visual dysfunction." (PMID 38646337, 2024). "Bilateral optic neuritis associated with optic disc swelling is a common feature of myelin oligodendrocyte glycoprotein antibody-associated disease (MOGAD)." (PMID 39569189, 2024). "MOG-IgG-associated disorders comprise a wide spectrum of syndromes ranging from acute-disseminated encephalomyelitis predominantly (ADEM) in children to optic neuritis or myelitis mostly in adults." (PMID 39334394, 2024). "We present a case of overlapping syndrome of MOG-IgG-associated disease and anti-mGluR5 encephalitis manifested as optic neuritis." (PMID 39151524, 2024). "Myelin oligodendrocyte glycoprotein (MOG) antibody-associated disorder (MOGAD) is a different disease entity that also affects the CNS with symptoms of optic neuritis, myelitis, and/or encephalomyelitis." (PMID 38343712, 2024). "Given the local prevalence data, serological testing for neuromyelitis optica spectrum disease (NMOSD) and myelin oligodendrocyte glycoprotein antibody-associated disease (MOGAD) is considered routine in optic neuritis investigation in Singapore." (PMID 39195624, 2024). "Here, we present a case of overlapping syndrome of MOG-IgG-associated disease and anti-mGluR5 encephalitis manifested as optic neuritis." (PMID 39151524, 2024). "This review aims to summarise current knowledge on MOG antibody-associated optic neuritis (MOG-ON), from presentation to diagnosis and treatment, in order to assist clinicians in managing this increasingly recognised condition." (PMID 38783085, 2024). "For example, a patient who presents with NMDAR encephalitis, but with associated optic neuritis or transverse myelitis, should alert the clinicians and should be tested for MOG-antibodies as well." (PMID 38804311, 2024). "Myelin oligodendrocyte glycoprotein (MOG) antibody-associated disease (MOGAD) is an acquired inflammatory demyelinating disease with optic neuritis (ON) as the most frequent clinical symptom." (PMID 36729854, 2023). "For instance, the emergence of protein conformation-dependent assays found autoantibodies against MOG in central nervous system (CNS), which can cause inflammatory demyelination to result in a myriad of CNS syndromes, including optic neuritis." (PMID 37104301, 2023). "The child was diagnosed with MOG-Ab-associated optic neuritis presenting as chronic relapsing inflammatory optic neuropathy (CRION)." (PMID 37565176, 2023). "The LCN2 and MOG-IgG correlation supports the immune and inflammatory nature of MOG-IgG positive optic neuritis, as LCN2 has been strongly associated with neuroinflammation." (PMID 35566760, 2022). "Among patients with bilateral optic neuritis, those associated with MOG-AD and parainfectious etiology report better visual recovery than NMOSD and autoantibody-associated disease, which carry a worse visual prognosis." (PMID 36072783, 2022). "In AQP4 Ab-associated optic neuritis, optic nerve damage depends on the severity of each attack; conversely, the nerve injury associated with MOG Abs seems to be related mainly to the frequency of attacks." (PMID 34997443, 2022). "Classical manifestations of MOG antibody-associated disease (MOGAD) that were initially described in the literature included optic neuritis, myelitis, brainstem demyelination and encephalitis." (PMID 36341089, 2022). "Patients with MOG-IgG–positive optic neuritis present with initially severe vision loss, are likely to have optic nerve head edema, and have favorable visual outcomes." (PMID 35566760, 2022).
optic neuritis (continued). "Optic neuritis (ON) is the most prevalent manifestation of pediatric multiple sclerosis (MSped) and myelin-oligodendrocyte glycoprotein antibody-associated disease (MOGADped) in children > 6 years." (PMID 35869995, 2022). "NMOSD associated with MOG antibodies presents with steroid responsive disease, bilateral concurrent optic neuritis, or transverse myelitis." (PMID 34484845, 2021). "MOG antibodies are more prevalent in demyelinating disorders (e.g., optic neuritis, ADEM), but can also be associated with encephalitis without demyelination." (PMID 34706651, 2021). "MOG-EM is associated with a broader clinical phenotype including optic neuritis, myelitis, brainstem lesions and acute disseminated encephalomyelitis with a substantial clinical and radiological overlap to other demyelinating CNS disorders." (PMID 32055995, 2020). "Most patients with MOG-IgG optic neuritis demonstrate a severe vision loss with eye pain at the onset, but favorable vision outcomes." (PMID 33374173, 2020). "The clinical phenotype associated with MOG-abs seropositivity in our cohort varied with age from ADEM in children (40%) to opticospinal (optic neuritis, myelitis and brainstem encephalitis) in adults." (PMID 33584514, 2020). "In C57B1/6 mice, active immunization with myelin oligodendrocyte glycoprotein peptide (MOG35–55) or adoptive transfer of MOG-specific T cells causes severe optic neuritis." (PMID 31684959, 2019). "MOG-IgG affinity-purified from the blood of patients with optic neuritis (ON) enhanced inflammation and induced demyelination upon transfer into experimental animals indicating the pathogenic potential of MOG-IgG detected in the blood of these patients." (PMID 31345223, 2019). "The patient was ultimately diagnosed with recurrent optic neuritis associated with MOG antibody seropositivity." (PMID 31163654, 2019). "Here, we describe a patient with highly relapsing optic neuritis (ON) associated with MOG-IgG1, whose ON attacks were relatively well-prevented with rituximab (RTX) treatment." (PMID 30577778, 2018). "CRION, according to the current diagnostic criteria, is a relapsing optic neuritis associated with MOG-IgG." (PMID 30382857, 2018). "Optic neuritis (ON) in patients with anti-myelin oligodendrocyte glycoprotein (MOG)-IgG antibodies has been associated with a better clinical outcome than anti-aquaporin 4 (AQP4)- IgG ON." (PMID 28125740, 2017). "An interesting syndrome associated with MOG-ADEM in children is the ADEM- optic neuritis (ADEM-ON or ADEMON) or multiphasic disseminated encephalomyelitis (MDEM-ON) complex." (PMID 29064441, 2017). "Distinctive clinical features in the MOG-seropositive group included the following: younger age at onset, increased predisposition to optic neuritis relapses, and improved prognosis." (PMID 29064441, 2017). "In MOG-antibody-associated optic neuritis, vaccination may also disrupt the blood-brain barrier, activating T-cells and triggering autoantibody production." (PMID 40026947, 2025). "ADEM: acute disseminated encephalomyelitis; CSF: cerebrospinal fluid; F: female; IVIG: intravenous immunoglobulin; IVMP: intravenous immunoglobulin; M: male; MMF: mycophenolate mofetil; MOGAD: Myelin oligodendrocyte glycoprotein antibody-associated disease; ON: optic neuritis." (PMID 41497944, 2025). "However, its application in demyelinating diseases, especially in the context of AQP4 and MOG antibody-associated optic neuritis pathogenesis, is yet to be fully explored." (PMID 39238786, 2024). "However, case–control studies examining the link between mild COVID-19 and isolated optic neuritis (ON) associated with MOG-Ab andAQP4-Ab within the same population are scarce." (PMID 38988608, 2024). "Interestingly, we found children more often demonstrated the typical supporting imaging features for MOG-IgG associated optic neuritis than adults." (PMID 39148657, 2024).
optic neuritis (continued). "Therefore, our results highlight the diagnostic value of plasma LCN2 levels for differentiating MOG-IgG–positive optic neuritis from MOG-IgG–negative optic neuritis." (PMID 35566760, 2022). "MOG-IgG–positive optic neuritis is a recently discovered cause of optic neuropathy." (PMID 35566760, 2022). "Therefore, our results indicate that plasma LCN2 levels can be used in clinical practice as a prompt diagnostic marker for MOG-IgG–positive optic neuritis." (PMID 35566760, 2022). "Overall, outcome is generally better in MOG-associated than in AQP4-associated optic neuritis." (PMID 34997443, 2022). "We plan to investigate the molecular mechanism underlying the increased plasma LCN2 levels in patients with MOG-IgG–positive optic neuritis with a focus on clinical factors that may influence plasma LCN2 levels in patients with MOG-IgG associated disorders." (PMID 35566760, 2022). "In addition, there are few heterogeneous case reports of optic neuritis with positive MOG-antibodies associated with Sars-CoV2 infection." (PMID 34706651, 2021). "One such example is the Myelin Oligodendrocyte Glycoprotein (MOG) antibody which is often associated with an acute disseminating encephalomyelitis (ADEM) but may also be associated with optic neuritis and encephalopathic features consistent with AE." (PMID 33854451, 2021). "Our group proposed the acronym MONEM to facilitate the identification of suspected cases as most the MOG-IgG+ patients present with attacks of Optic Neuritis (ON), Encephalitis, and/or Myelitis, but some other groups have used the term MOG-associated disorder (MOGAD)." (PMID 34025652, 2021). "Moreover, IFN-β-1a caused a slight decrease in the loss of RGCs in a mouse MOG-induced optic neuritis model." (PMID 32545828, 2020). "Autoantibodies to myelin oligodendrocyte glycoprotein (MOG) are associated with a relatively stereotyped set of clinical presentations including recurrent optic neuritis, acute disseminated encephalomyelitis, pediatric acquired demyelinating syndrome, and NMOSD without AQP4 autoantibodies." (PMID 30824481, 2019). "The presence of MOG Ab has been most commonly associated with monophasic and recurrent episodes of optic neuritis (ON), acute disseminated encephalomyelitis (ADEM), and transverse myelitis (TM) in children, as well as unilateral ON, bilateral ON, and TM in adults." (PMID 31481127, 2019). "Therefore, we propose the term MOG-IgG-associated Optic Neuritis, Encephalitis, and Myelitis (MONEM)." (PMID 29670575, 2018). "As further verification that axonal loss from optic neuritis was the likely source of the pNF-H in ONTT patients, we turned to transgenic TCR MOG mice that develop only optic neuritis that in turn causes loss of retinal ganglion cells and their optic nerve axons." (PMID 22096624, 2010). "A "Devic-like" disease, characterized by spontaneous optic neuritis and paralysis associated with spinal cord inflammation occurred when myelin oligodendrocyte glycoprotein (MOG)-specific T cell receptor (TCR) transgenic (Tg) mice were crossed to MOG-specific B cell receptor (BCR) knock-in mice." (PMID 21151500, 2010). "Myelin oligodendrocyte glycoprotein antibody-associated disease (MOGAD) is an inflammatory demyelinating disorder that frequently presents with optic neuritis or myelitis, although early diagnostic evaluation may be challenging when neuroimaging is normal despite significant neurological deficits." (PMID 41583138, 2025). "Myelin oligodendrocyte glycoprotein-immunoglobulin G associated disease (MOGAD) is an autoimmune demyelinating disorder of the central nervous system (CNS) which usually occurs with recurrent optic neuritis, transverse myelitis, acute disseminating encephalomyelitis, or brainstem encephalitis." (PMID 38010585, 2024).
optic neuritis (continued). "Further studies are needed to elucidate whether OLE action may protect from loss of RGCs and visual function in MOG-induced optic neuritis, given that both accumulation of oxidative stress and demyelination in the optic tract nerves, were substantially reduced in our mice model under OLE treatment." (PMID 33233421, 2020). "The frequency of AQP4, glycine receptor alpha 1 subunit, and MOG antibodies was determined in a cohort of patients with isolated optic neuritis; the combination was found in 45% (23 of 51) of the cases of the cases and was associated with unilateral or bilateral, severe or recurrent optic neuritis." (PMID 29064441, 2017). "An early and accurate diagnosis of myelin oligodendrocyte glycoprotein antibody seropositive optic neuritis (MOG-ON) versus seronegative-ON is critical for optimal management." (PMID 41017978, 2025). "The most common presentation of MOGAD was optic neuritis (6/16; 37.5%), and 15/16 (93.8%) had clear positive serum MOG‐IgG, while one (6.3%) had isolated CSF MOG‐IgG‐positivity." (PMID 39932929, 2025). "Management of optic neuritis can be challenging due to decisions for treatment being required prior to availability of supporting evidence (MRI, NMO serology, MOG serology) to triage as to the underlying cause." (PMID 40606143, 2025). "Elevated levels of autoantibodies against MOG have been detected in various demyelinating conditions, encompassing optic neuritis, transverse myelitis, acute disseminated encephalomyelitis, and cerebral cortical encephalitis." (PMID 39522688, 2025). "She met the definition criteria of ADEM-ON, which includes any episode of ADEM with one or more episodes of optic neuritis together with positive serum of MOG-antibody, patient fulfils the criteria of MOGAD." (PMID 40600086, 2025). "Although distinct from demyelinating optic neuritis, it is also found in demyelinating optic neuritis (especially myelin oligodendrocyte glycoprotein optic neuritis)." (PMID 40041467, 2025). "Regardless of age, careful fundus examination is necessary during the clinical course of optic neuritis, and MOG-immunoglobulin G testing can be considered for patients showing optic neuritis with AMN." (PMID 40265085, 2025). "The decision by the tertiary center to initiate PLEX before the MOG-IgG result returned aligns with recommendations for severe or progressive optic neuritis and myelitis, particularly when visual acuity is significantly impaired." (PMID 41583138, 2025). "A case in point is the prevalence of MOG autoantibodies among patients with demyelinating disorders, such as MS and optic neuritis, which is estimated between 0.3–5%, compared with a prevalence of 0–1.3% among healthy individuals." (PMID 40757033, 2025). "Myelin oligodendrocyte glycoprotein (MOG) antibody‐associated disease (MOGAD) is a relatively recently described disease, most commonly presenting with optic neuritis and longitudinally extensive transverse myelitis." (PMID 39560205, 2025). "Vision loss associated with optic neuritis in patients with NMOSD and MOG is usually more severe and results in larger scotomas, areas of complete or partial visual field loss." (PMID 40002778, 2025). "Nevertheless, specialized literature also discusses rare occurrences of optic neuritis attacks during the first trimester of pregnancy and rare cases of myelin oligodendrocyte glycoprotein optic neuritis (MOG-ON)." (PMID 38672703, 2024). "The spectrum of demyelinating disorders with IgG antibodies to MOG, known as MOG antibody-associated disease (MOGAD), includes optic neuritis, encephalitis, myelitis, acute disseminated encephalomyelitis (ADEM), and other variants." (PMID 39479094, 2024). "MOG antibodies (MOG-Ab) were also associated with NMOSD, particularly in cases of bilateral optic neuritis." (PMID 39364495, 2024). "A 2016 study of 50 patients with MOG-IgG-positive transverse myelitis or optic neuritis reported that 15 patients (30%) had a history of brainstem encephalitis." (PMID 39830197, 2024).